NGFR (nerve growth factor receptor)
Diseases named in the same sentence as NGFR in open-access papers (continued):
Sharing a sentence is not in itself a finding about the gene and the disease.
leprosy (3 papers, 2018 to 2024). Leprosy is a chronic infectious disease affecting primarily the skin and peripheral nervous system. "In addition, we determined the levels of NGF and NGFR in leprosy lesion using real-time polymerase chain reaction (PCR)." (PMID 36389696, 2022). "In contrast, the expressions of NGF and NGFR were negatively correlated with the proportion of dermal IL-17A–producing γδ T cells, indicating negatively regulation of IL-17A+ γδ T cells on NGF and NGFR expression in lesion of TT leprosy." (PMID 36389696, 2022).
malignant glioma (3 papers, 2008 to 2021). A grade III or grade IV glioma arising from the central nervous system. "Finally, we analyzed the expression of p16, NGFR, WT1 and MME in 37 DIPG patient samples with H3.3K27M mutation and 58 non-brainstem pediatric high-grade glioma (NBS-HGG) samples with wild type H3.3 using the public database." (PMID 29932419, 2018).
non-small cell lung carcinoma (3 papers, 2016 to 2025). A group of at least three distinct histological types of lung cancer, including non-small cell squamous cell carcinoma, adenocarcinoma, and large cell carcinoma. "Based on a new study, resveratrol stimulates the NGFR downstream pathway AMPK-mTOR to induce autophagy in non-small-cell lung cancer cells." (PMID 40758712, 2025). "Resveratrol (RSV) has been reported to induce autophagy and apoptosis in non-small-cell lung cancer A549 cells, and the nerve growth factor receptor (NGFR) regulates autophagy and apoptosis in many other cells." (PMID 35745143, 2022).
oral squamous cell carcinoma (3 papers, 2014 to 2019). "Here, we investigated the mechanism by which NGFR affects invasion and tumor progression in a murine oral squamous cell carcinoma (MOC) model and identified an important downstream target of NGFR to be a gene called ESM1." (PMID 27683113, 2016). "A recent study revealed that ESM1 could mediate nerve growth factor receptor (NGFR)-induced invasion and metastasis in murine oral squamous cell carcinoma." (PMID 31073279, 2019).
systemic lupus erythematosus (3 papers, 2023 to 2025). An autoimmune multi-organ disease typically associated with vasculopathy and autoantibody production. "Our study also found systemic lupus erythematosus, cytokine-cytokine receptor interaction, and arachidonic acid metabolism were associated with DME/NGFR-high samples." (PMID 39347501, 2024). "Similarly, complement and coagulation cascades, cytokine-cytokine receptor interaction, arachidonic acid metabolism, systemic lupus erythematosus, ecm receptor interaction are also significantly overrepresented in NGFR-high samples." (PMID 39347501, 2024). "Overexpression of NGFR may affect the immunity and inflammatory pathway, such as complement and coagulation cascades, systemic lupus erythematosus, cytokine-cytokine receptor interaction, arachidonic acid metabolism." (PMID 39347501, 2024). "According to the KEGG pathway, the complement and coagulation cascades, systemic lupus erythematosus, cytokine-cytokine receptor interaction, arachidonic acid metabolism were significantly over-represented in DME and NGFR-high samples." (PMID 39347501, 2024).
type 2 diabetes (3 papers, 2012 to 2018). "Regarding NGFR gene rs734194 SNP, its minor allele showed association with TOAST small artery occlusion (p = 0.02), Type 2 diabetes (p = 0.019), height (p = 0.019), serum cystatin C (p = 0.016)." (PMID 29499660, 2018).
anhidrosis (2 papers, 2013 to 2019). Lack of sweating or the ability to sweat when provoked by the appropriate stimulus. "Congenital insensitivity to pain with anhidrosis (CIPA) is a rare inherited disorder of the peripheral nervous system resulting from mutations in neurotrophic tyrosine kinase receptor 1 gene (NTRK1), which encodes the high-affinity nerve growth factor receptor TRKA." (PMID 23799134, 2013).
Cerebrovascular Disease (2 papers, 2015 to 2018). "According to the data of Cerebrovascular Disease Knowledge Portal most recent GWAS have discovered associations between the studied sequence variants in NGF and NGFR gene and cerebrovascular disease or related traits." (PMID 29499660, 2018).
cervical carcinoma (2 papers, 2022 to 2024). A carcinoma arising from either the exocervical squamous epithelium or the endocervical glandular epithelium. "The reprogramming-related genes, including transcription factors (CJUN), myelin genes (MBP), neurotrophic factors and receptors (BDNF, NGFR) and axonal regenerative marker (GAP43) were significantly elevated upon RSC96 cells co-cultured with cervical cancer cells." (PMID 39214988, 2024).
chronic pancreatitis (2 papers, 2012 to 2025). A chronic inflammatory process causing damage and fibrosis of the pancreatic parenchyma. "Alongside ADM, NGFR+/PDGFRα+ stromal cells delineate a remodeled lobular niche characterized by injury and chronic pancreatitis-like features, possibly providing a distinct microenvironment modifying tumor cell behaviour." (PMID 41006303, 2025). "During routine pathology assessment of clinical samples, we consistently observed strong stromal NGFR expression in lobular regions exhibiting features of chronic pancreatitis and morphological signs of tissue injury." (PMID 41006303, 2025). "Next, we compared NGFR expression between lobules exhibiting peritumoral chronic pancreatitis without tumor invasion and those with tumor invasion, which were consistently associated with tissue injury." (PMID 41006303, 2025).
Cirrhosis (2 papers, 2015 to 2023). A chronic disorder of the liver in which liver tissue becomes scarred and is partially replaced by regenerative nodules and fibrotic tissue resulting in loss of liver function. "In cirrhosis, we observed a similar NGFR+ stroma, condensing with higher degrees of liver plate atrophy." (PMID 37596278, 2023).
cutaneous melanoma (2 papers, 2018 to 2021). A primary melanoma arising from atypical melanocytes in the skin. "In UVM lines, however, the protein expression of HLA-DR, NGFR, PD-L1, and PD-L2 post-IFNγ stimulation was significantly lower than observed in cutaneous melanomas, and this was consistent with low baseline expression of HLA-DR, NGFR, and PD-L2 in the UVM cells." (PMID 29977240, 2018). "We also noted that cell surface expression of HLA-DR, NGFR, and PD-L2 was significantly lower in UVM compared to cutaneous melanoma, both at baseline and post-IFNγ stimulation." (PMID 29977240, 2018). "In particular, HLA-DR, NGFR, and PD-L2 cell surface expression was significantly lower in the UVM cell subset compared to cutaneous melanoma." (PMID 29977240, 2018). "Three cutaneous melanoma cell lines (C013M, MeWo and NM177) were classified as transitory, as they expressed elevated levels of MITF and Melan A, and intermediate/high levels of AXL and/or NGFR." (PMID 34073253, 2021).
HIV-1 infection (2 papers, 2016 to 2024). The type species of lentivirus and the etiologic agent of acquired immunodeficiency syndrome (AIDS). "HIV-1 peptides containing 36 or 46 amino acids from HR2 have been shown to inhibit HIV-1 infection in primary T cells when conjugated to membrane-associated scaffold proteins derived from the nerve growth factor receptor or CD34." (PMID 27855210, 2016).
infarction (2 papers, 2018 to 2019). A localised pathological necrosis of tissue resulting from obstruction of the blood supply usually by a thrombus, an embolus, or vascular torsion. "However, this is the first study to evaluate the association of the genetic variations of the NGF and the NGFR genes with IS, infarction size and recurrence of the disease in Armenian population." (PMID 29499660, 2018).
intrahepatic cholangiocarcinoma (2 papers, 2023 to 2025). A carcinoma that arises from the intrahepatic bile duct epithelium in any site of the intrahepatic biliary tree. "Multiplex-IF of intrahepatic cholangiocarcinoma revealed stromal protein gradients similar to those observed in CRLM, which were characterized by ASMA, NGFR, and PDGFRa at the outer edge, and FAP and PDGFRb at the inner side of the rim." (PMID 37596278, 2023).
liver cancer (2 papers, 2021 to 2023). An epithelial or non-epithelial malignant neoplasm that arises from the liver. "Meanwhile, DEPDC1, DEPDC1B, CALCRL, PRR11, and TRIP13 were significantly upregulated in liver cancer tissue, yet NGFR was downregulated." (PMID 36785674, 2023).
myelofibrosis (2 papers, 2018 to 2022). A partial or complete replacement of the bone marrow stroma by fibrous tissue. "Though p-ERK1-2 immunoreaction proved to be another biomarker of bone marrow stromal cell activation and myelofibrosis evolution it showed less potential than NGFR reaction for diagnostic use." (PMID 35356507, 2022).
myeloma (2 papers, 2018 to 2019). "The NGF receptors TrkA (encoded by NTRK1) and p75NTR (encoded by NGFR) were not strongly or consistently expressed by MM cell lines, which was consistent with a lack of effect of recombinant NGF on myeloma cell growth." (PMID 31578352, 2019).
neuropathy (2 papers, 2013 to 2018). A disorder affecting the nervous system that manifests with pain, tingling, numbness, and/or muscle weakness. "Despite this, we showed that the expression especially of NGF, NGFR, NTRK1, GFRA1, GFAP, and GDNF was upregulated in patients with severe neuropathy as compared to healthy subjects and diabetic patients with subclinical neuropathy." (PMID 30648113, 2018).
renal fibrosis (2 papers, 2018 to 2023). A final common manifestation of a wide variety of chronic kidney diseases characterized by glomerulosclerosis and tubulointerstitial fibrosis. "In UUO model group, Tgfβ1/Smad2/3 pathway, Wnt4/β-Catenin pathway, and NGFR/NF-κB pathway were activated, which led to inflammatory response and accelerated cell proliferation, thus promoting the progression of renal fibrosis." (PMID 37198665, 2023). "Therefore, our study demonstrated that RSGB suppressed the inflammatory response and cell cycle by inhibiting the Tgfβ1/Smad2/3 pathway, Wnt4/β-Catenin pathway and NGFR/NF-κB pathway, thereby exerting an anti-renal fibrosis effect." (PMID 37198665, 2023). "In conclusion, our study, for the first time, identified the chemical constituents in RSGB by UPLC-QTOF-MS/MS and demonstrate that the improvement of renal fibrosis by RSGB is related to the inhibition of Tgfβ1/Smad2/3 pathway, Wnt4/β-catenin pathway and NGFR/NF-κB pathway." (PMID 37198665, 2023).
teratoma (2 papers, 2023 to 2025). A non-seminomatous germ cell tumor characterized by the presence of various tissues which correspond to the different germinal layers (endoderm, mesoderm, and ectoderm). "Nevertheless, when combined with CD82 and ERBB3, the use of NGFR further purified the skeletal myogenic population in human teratomas." (PMID 36766703, 2023). "In the current study, we have demonstrated that an expandable and engraftable CD82+ERBB3+NGFR+ skeletal myogenic progenitor population can be produced from human PSCs via teratoma formation." (PMID 36766703, 2023). "Teratomas were enzymatically digested and mechanically dissociated to produce a single-cell suspension, stained for CD82, ERBB3, and NGFR, and the triple-positive population, representing approximately 2% of total teratoma-derived cells, isolated by fluorescence-activated cell sorting (FACS)." (PMID 40801582, 2025). "This as somewhat expected, given that in our previous single-cell RNA-seq analysis of human teratomas, we did not detect NGFR as a standalone skeletal myogenic surface marker, but rather found NGFR to be present in diverse cell populations." (PMID 36766703, 2023).
triple-negative breast carcinoma (2 papers, 2021 to 2023). An invasive breast carcinoma which is negative for expression of estrogen receptor (ER), progesterone receptor (PR), and human epidermal growth factor receptor 2 (HER2). "Until recently, the association between NGFR and chemoresistance was reported in triple-negative breast cancer cells." (PMID 33996571, 2021).
type 1 diabetes (2 papers, 2020 to 2024). "In the STZ-induced mouse model of type 1 diabetes, NGFR mediates the release of ligand-dependent inflammatory cytokines, disrupts glial-vascular units, and promotes blood-retinal barrier breakdown." (PMID 39347501, 2024).
adenoma (1 paper, 2025). A neoplasm arising from the epithelium. "Transdifferentiation theory: suggests that neuronal differentiation of preexisting adenoma cells is mediated via nerve growth factor (NGF) and its receptor NGFR, which have been detected in some adenoma subtypes." (PMID 41346449, 2025).
ameloblastoma (1 paper, 2020). The most common odontogenic tumor, arising from the epithelial component of the embryonic tooth and usually affecting the molar-ramus region of the mandible or maxilla. "P75/NGFR was expressed at high levels throughout the ameloblastoma epithelium, as well as in stromal regions associated to NGF expression." (PMID 32155948, 2020). "We have shown that the ameloblastoma epithelium expresses detectable levels of the neurotrophins NGF and BDNF, as well as the neurotrophin receptors TRKA, TRKB, and P75/NGFR." (PMID 32155948, 2020). "Using immunofluorescent staining, we detected expression of the neurotrophins NGF (Nerve Growth Factor) and BDNF (Brain Derived Neurotrophic Factor), as well as their receptors P75/NGFR, TRKA and TRKB, in human ameloblastoma biopsies." (PMID 32155948, 2020). "Additionally, we showed that ameloblastomas express the neurotrophic factors NGF and BDNF, as well as their receptors TRKA, TRKB, and P75/NGFR, which are responsible for their innervation by trigeminal axons in vivo." (PMID 32155948, 2020).
anaplastic large cell lymphoma (1 paper, 2008). Anaplastic large cell lymphoma (ALCL) is a rare and aggressive peripheral T-cell non-Hodgkin lymphoma, belonging to the group of CD30-positive lymphoproliferative disorders, which affects lymph nodes and extranodal sites. "CD30, a 120 kDa surface phosphorylated protein is a member of tumour necrosis/nerve growth factor receptor (TNF/NGFR) family and constitutively expressed by Hodgkin and Reed-Sternberg (HRS) cells of Hodgkin lymphoma (HL) and the neoplastic cells of Anaplastic Large Cell Lymphoma (ALCL)." (PMID 18218123, 2008).
arterial diseases (1 paper, 2018). "NGFR, also known as p75NTR, is a neurotrophin receptor that is involved in the pathogenesis of arterial diseases, which is highly expressed in the atherosclerotic adventitia." (PMID 30134788, 2018).
bladder disorders (1 paper, 2021). "There are still many unresolved issues concerning the role of NGF and its receptor NGFR p75 in the pathophysiology of bladder disorders." (PMID 33692976, 2021). "Increased distribution of NGF or NGFR p 75 in the urothelium is more often reported in painful bladder disorders, whereas higher levels of NGF or NGFR p75 have been described for the submucosal tissue and detrusor in functional bladder alterations." (PMID 33692976, 2021).
bladder exstrophy (1 paper, 2021). Bladder exstrophy (or classic bladder exstrophy; CEB) is a congenital genitourinary malformation belonging to the spectrum of the exstrophy-epispadias complex (EEC) and is characterized by an evaginated bladder plate, epispadias and an anterior defect of the pelvis, pelvic floor and abdominal wall. "Observation of NGFR p75 in the urothelium and detrusor in biopsies from patients with bladder exstrophy (BE) obtained during primary closure and from patients with congenital vesicoureterorenal reflux (VUR) obtained during reflux surgery who served as controls." (PMID 33692976, 2021).
Burkitt lymphoma (1 paper, 2015). A rare form of malignant mature B-cell non-Hodgkin lymphoma. "Cells from a Burkitt’s lymphoma which harbor EBV in type I latency had previously been engineered to co-express Green Fluorescent Protein (GFP), Nerve Growth Factor receptor (NGFR) and Zta (BZLF1) from an inducible bi-directional promoter (Akata-Zta)." (PMID 26529022, 2015).
cholangitis (1 paper, 2023). An acute or chronic inflammatory process affecting the biliary tract. "We found that the fibrous stroma in focal nodular hyperplasia and cholangitis was NGFR+, akin to the outer region of the capsule." (PMID 37596278, 2023).
cholesteatoma (1 paper, 2015). A pathologic process characterized by the proliferation of keratinizing squamous epithelium resulting in the accumulation of keratin and cells in the middle ear and/or mastoid. "Furthermore, mRNA encoding IKK2 and NGFR (Nerve Growth Factor Receptor), which has many different roles, including stimulating cells to survive and differentiate, were downregulated in cholesteatoma compared to EAS samples." (PMID 25922834, 2015). "Moreover downregulation of NGFR in cholesteatoma might inhibit the process of cell survival and differentiation and inhibit the cell death restoration, which could be demonstrated in other cells." (PMID 25922834, 2015).
colon adenocarcinoma (1 paper, 2019). "Methylation of the ESR1, MGMT, HPP1/TPEF, HLTF, and NGFR genes is associated with the onset of colon adenocarcinoma and occurs during the early stages of oncogenesis." (PMID 31852837, 2019).
colorectal adenocarcinoma (1 paper, 2022). The most common type of colorectal carcinoma. "Moreover, expression of the majority of the genes (CACNA1H, COL1A1, COL11A1, FZD8, NGFR, SFRP2, WNT2B, and WNT5A) was associated with the ‘mesenchymal’ CMS group 4 in the TCGA (The Cancer Genome Atlas) Colorectal Adenocarcinoma dataset." (PMID 35892888, 2022).
ductal breast carcinomas (1 paper, 2025). "A multi-cohort microarray study revealed that only 4.5% of 245 viable invasive breast carcinoma and 38% of 37 high-grade basal-like ductal breast carcinoma samples were NGFR positive, supporting the role of NGFR as a tumor suppressor." (PMID 40732340, 2025).
Fibroadenoma (1 paper, 2025). A benign tumor of the breast characterized by the presence of stromal and epithelial elements. "Immunohistochemistry studies using paraffin-embedded tissue samples from normal breast myoepithelial cells, benign breast lesions, and fibroadenomas (non-cancerous tumors) revealed strong reactivity of NGFR." (PMID 40732340, 2025).
generalized anxiety disorder (1 paper, 2022). An anxiety disorder characterized by excessive and difficult-to-control worry about a number of life situations. "miR-4505 is reportedly involved in the nervous system, midbrain development, and nerve growth factor receptor signaling pathways, and its overexpression has been associated with the onset of generalized anxiety disorder." (PMID 36077842, 2022).
Hernia (1 paper, 2022). "The average percentage immunohistochemical positive cells to NGF and NGFR p75 of 15 biopsies excised from the 3D dynamic hernia scaffold at different stages post implantation were compared with a one-way Anova and post hoc Tuckey test." (PMID 36412894, 2022).
influenza (1 paper, 2023). An acute viral infection of the respiratory tract, occurring in isolated cases, in epidemics, or in pandemics; it is caused by serologically different strains of viruses (influenzaviruses) designated A, B, and C, has a 3-day incubation period, and usually lasts for 3 to 10 days. "Histologically, influenza- but not SARS-CoV-2-infected mice showed extensive Krt5+ “pods” structure co-stained with stem cell markers Trp63/NGFR proliferated in the pulmonary consolidation area at both 7 and 14 DPI, with regression at 21 DPI." (PMID 38092883, 2023).
invasive ductal carcinoma (1 paper, 2022). "Moreover, NGFR/p75NTR appears to also be involved in the proliferation and metastatization of invasive ductal carcinoma through the NF-kB pathway, as demonstrated on MCF-7 cell." (PMID 36354700, 2022).